COG4 (component of oligomeric golgi complex 4)
Description:
Required for normal Golgi function. Plays a role in SNARE-pin assembly and Golgi-to-ER retrograde transport via its interaction with SCFD1.
Synonyms: COD1; DKFZP586E1519; CDG2J; SWILS
Tractability: Antibody: UniProt places it where antibodies can reach, with high confidence. PROTAC: ubiquitination databases record sites on it; its protein half-life has been measured.
Target class: Other cytosolic protein
Gene: Protein-coding gene on chromosome 16 (70,480,568 to 70,523,560, reverse strand). Ensembl gene ENSG00000103051.
Subcellular location: Cytoplasm, cytosol; Golgi apparatus membrane
Subcellular location (Human Protein Atlas): Golgi apparatus; Vesicles
Pathways (Reactome):
Vesicle-mediated transport: COPI-mediated anterograde transport; Intra-Golgi traffic; Retrograde transport at the Trans-Golgi-Network
Gene Ontology:
Molecular function: protein binding
Biological process: Golgi organization; retrograde transport, vesicle recycling within Golgi; retrograde vesicle-mediated transport, Golgi to endoplasmic reticulum
Cellular component: Golgi transport complex; Golgi membrane; trans-Golgi network membrane; cytosol
Genetic constraint (gnomAD): Loss-of-function variants: 62 observed, 95.17 expected, observed/expected ratio (o/e) 0.65, 90% interval 0.53 to 0.81. The upper end of that interval is the gene's LOEUF score, 0.81, which puts it in group 3 of 6, group 1 being the genes least tolerant of losing a copy. Missense variants: 1,022 observed, 1,021.6 expected, observed/expected ratio (o/e) 1, 90% interval 0.95 to 1.05. Synonymous variants: 416 observed, 392.36 expected, observed/expected ratio (o/e) 1.06, 90% interval 0.98 to 1.15.
Gene-disease validity (ClinGen):
ClinGen rates the evidence that COG4 causes each of these diseases.
microcephalic osteodysplastic dysplasia, Saul-Wilson type (autosomal dominant): Definitive. A bone development disease characterized by early developmental delay primarily involving speech, distinct facial features, short stature, brachydactyly, clubfoot deformities, cataracts, and microcephaly that has material basis in heterozygous mutation in COG4 on chromosome 16q22.1.
COG4-congenital disorder of glycosylation (autosomal recessive): Moderate. COG4-CDG is an extremely rare form of CDG syndrome characterized clinically in the single reported case to date by seizures, some dysmorphic features, axial hyponia, slight peripheral hypertonia and hyperreflexia.
Homologues: Orthologues: chimpanzee COG4 (99% identical), macaque COG4 (99% identical), pig COG4 (97% identical), rabbit COG4 (96% identical), dog COG4 (94% identical), rat Cog4 (94% identical), guinea pig COG4 (94% identical), mouse Cog4 (94% identical), tropical clawed frog cog4 (80% identical), zebrafish cog4 (71% identical), Drosophila melanogaster Cog4 (38% identical), Caenorhabditis elegans cogc-4 (32% identical). Paralogues in human: DNAJC28 (9% identical).
Diseases named in the same sentence as COG4 in open-access papers:
COG4 is named in the same sentence as 19 diseases in open-access papers, as found by Europe PMC text mining. Sharing a sentence is not in itself a finding about the gene and the disease. The quoted sentences say what the papers report.
Saul-Wilson syndrome (8 papers, 2021 to 2026). "Among these, COG4 is a potential candidate gene since it is the causal gene for the Saul-Wilson syndrome causing dwarfism and skeletal abnormalities in humans, and is associated with reduced body length in zebrafish." (PMID 38017417, 2023). "Some disorders have also been reclassified as CDG as the expansion of their pathophysiological mechanisms has included underlying glycosylation defects (e.g., Saul-Wilson syndrome [COG4], Cowden syndrome 7 [SEC23B], ALG5- and ALG9-CDG)." (PMID 37858231, 2023). "Saul-Wilson syndrome is a rare skeletal dysplasia caused by a heterozygous mutation in COG4 (p.G516R)." (PMID 36393834, 2022). "Recently, a rare skeletal dysplasia has been discovered caused by a specific heterozygous COG4 substitution (p.G516R) named Saul-Wilson syndrome (SWS)." (PMID 34603392, 2021). "Saul-Wilson syndrome due to COG4 G516R mutation results in a rare skeletal dysplasia which is not categorized as CDG as defined in COG4 mutation R729W." (PMID 34603392, 2021). "To test this novel strategy, we created RPE1 and HEK293T cells expressing COG4 mutations COG4-G516R (Saul-Wilson syndrome) and COG4-R729W (COG-CDG type IIj) under the endogenous COG4 promoter." (PMID 34603392, 2021). "Saul-Wilson syndrome (SWS) is a skeletal dysplasia characterized by primordial dwarfism and progeroid features caused by a recurrent dominant COG4 variant (p.G516R)." (PMID 42039558, 2026). "Interestingly, the clinical phenotype of patients with congenital mutations in the SIL1 gene (Marinesco-Sjogren syndrome) overlaps with the phenotype of COG4-G516R patients (Saul-Wilson syndrome)." (PMID 34603392, 2021).
chondrosarcoma (1 paper, 2022). A malignant cartilaginous matrix-producing mesenchymal neoplasm arising from the bone and soft tissue. "We first fluorescently labeled WT, COG4p.G516R, and COG4-KO chondrosarcoma cells by expressing cytosolic RFP or GFP." (PMID 36393834, 2022). "In both COG4p.G516R and COG4-KO chondrosarcoma cells, secretion of some proteoglycans was significantly altered." (PMID 36393834, 2022). "We observed some altered protein bands in chondrosarcoma COG4 mutant cells which were not seen in cell lysates." (PMID 36393834, 2022).
hearing loss (1 paper, 2023). "COG4, which was also associated with Sensory hearing loss, is strongly expressed in hair cells and Deiters cells, and is known to be important for zebrafish inner ear development." (PMID 38011198, 2023).
intellectual disabilities (1 paper, 2021). "COG4-CDG individuals have a very severe, usually lethal, phenotype with dysmorphia, neurological and intellectual disabilities, and altered N-glycosylation with an almost total loss of COG4." (PMID 34595172, 2021).
viral infection (1 paper, 2020). "The increased cell survival to synthetic dsRNA transfection and viral infection of COG4 KO cells compared to WT cells opens several interesting perspectives." (PMID 33177215, 2020).
skeletal dysplasia (4 papers, 2021 to 2026). Any Mendelian diseases that affects growth and development of the skeleton. "COG4-CDG is a skeletal dysplasia characterized by short stature, distinctive craniofacial features, short fingers and toes." (PMID 40993721, 2025). "While these results indicate a critical function of COG4 in Golgi processing, the developmental process leading to skeletal dysplasia in SWS patients remains unknown." (PMID 42039558, 2026).
genetic disorders (1 paper, 2022). "COG4 is a protein involved in protein trafficking and glycosylation, and its mutations cause both dominant and recessive human genetic disorders, SWS and COG-CDG, respectively." (PMID 36393834, 2022).
infection (1 paper, 2020). The state of being infected such as from the introduction of a foreign agent such as serum, vaccine, antigenic substance or organism. "Nonetheless, cell death induced by dsRNA appears to be lower in COG4 KO cells, most likely due to a delay in the infection." (PMID 33177215, 2020). "Overall, our results indicate that COG4 expression is needed for an efficient SINV infection and that its absence can delay the infection, thereby increasing cell survival in COG4 KO cells." (PMID 33177215, 2020). "In agreement, the determination of viral titer by plaque assay showed that COG4 KO HEK293T cells produced significantly fewer infectious viral particles than HEK293T or COG4-rescued cells at 24 hpi but not at 48 hpi, underlining a possible delay in the infection and virus-induced cell death." (PMID 33177215, 2020).
tumour (1 paper, 2021). "mRNA expression levels of COG subtypes depended on the tumour grade, especially COG4, COG5, COG6, COG7, and COG8." (PMID 34539936, 2021). "Similarly, high mRNA expression of 5 of all COG isoforms (COG2, COG3, COG5, COG6, COG7, and COG8) was also correlated with favourable OS of KIRC patients with tumour grade 2, grade 3, and grade 4, while patients with low mRNA expression of COG4 showed higher survival rate." (PMID 34539936, 2021).
COG4 also shares sentences with these, for which no sentence is quoted: Arrhythmia (1 paper); Cerebellar atrophy (1); cervical cancer (1); cholestasis (1); congenital disorder of glycosylation (1); dwarfism (1); Failure to thrive (1); keratosis pilaris (1); Marinesco-Sjogren syndrome (1); primordial dwarfism (1).